MIR3652 (microRNA 3652)
Synonyms: hsa-mir-3652
Gene: MicroRNA gene on chromosome 12 (103,930,425 to 103,930,555, forward strand). Ensembl gene ENSG00000284503.
Diseases named in the same sentence as MIR3652 in open-access papers:
MIR3652 is named in the same sentence as 2 diseases in open-access papers, as found by Europe PMC text mining. Sharing a sentence is not in itself a finding about the gene and the disease.
MIR3652 shares sentences with these, for which no sentence is quoted: psychiatric disorder (1 paper); schizophrenia (1).